PSMG3 (proteasome assembly chaperone 3)
Description:
Chaperone protein which promotes assembly of the 20S proteasome. May cooperate with PSMG1-PSMG2 heterodimers to orchestrate the correct assembly of proteasomes.
Synonyms: Pba3; C7orf48; PAC3; MGC10911
Tractability: Small molecule: it belongs to a druggable protein family. PROTAC: ubiquitination databases record sites on it; its protein half-life has been measured; a small molecule that binds it is known.
Gene: Protein-coding gene on chromosome 7 (1,567,332 to 1,571,078, reverse strand). Ensembl gene ENSG00000157778.
Pathways (Reactome):
Metabolism of proteins: Proteasome assembly
Gene Ontology:
Molecular function: molecular adaptor activity; protein binding; protein-containing complex binding
Biological process: chaperone-mediated protein complex assembly; proteasome core complex assembly; proteasome assembly
Cellular component: protein folding chaperone complex; cytosol; protein-containing complex
Genetic constraint (gnomAD): Loss-of-function variants: 4 observed, 8.61 expected, observed/expected ratio (o/e) 0.46, 90% interval 0.23 to 1.06. That is too few expected variants to judge how well the gene tolerates losing a copy. Missense variants: 151 observed, 165.57 expected, observed/expected ratio (o/e) 0.91, 90% interval 0.8 to 1.04. Synonymous variants: 81 observed, 74.15 expected, observed/expected ratio (o/e) 1.09, 90% interval 0.91 to 1.31.
Homologues: Orthologues: chimpanzee PSMG3 (100% identical), macaque PSMG3 (99% identical), guinea pig PSMG3 (93% identical), mouse Psmg3 (92% identical), rat Psmg3 (89% identical), pig PSMG3 (89% identical), dog PSMG3 (84% identical), tropical clawed frog psmg3 (66% identical), zebrafish psmg3 (52% identical).
Diseases named in the same sentence as PSMG3 in open-access papers:
PSMG3 is named in the same sentence as 11 diseases in open-access papers, as found by Europe PMC text mining. Sharing a sentence is not in itself a finding about the gene and the disease. The quoted sentences say what the papers report.
breast carcinoma (1 paper, 2026). "Among these chaperones, PSMG3 is uniquely and markedly elevated in breast cancer and is associated with poor clinical outcomes." (PMID 41869439, 2026). "This integrative multi-omics analysis identified PSMG3 as a clinically relevant proteasome assembly chaperone associated with aggressive breast cancer phenotypes, metabolic dysregulation, and tumor immune contexture." (PMID 41869439, 2026). "Elevated PSMG3 expression was consistently associated with poor survival outcomes across multiple breast cancer cohorts." (PMID 41869439, 2026). "Collectively, these results highlight PSMG3 as a promising prognostic biomarker and potential therapeutic target in breast cancer." (PMID 41869439, 2026). "The proteasome assembly chaperone (PSMG) gene family (comprised of PSMG1, PSMG2, PSMG3, and PSMG4) plays a critical role in proteasome biogenesis; however, its involvement in breast cancer remains poorly understood." (PMID 41869439, 2026).
glioblastoma (1 paper, 2023). The most malignant astrocytic tumor (WHO grade IV). "Elevated PSMG3 levels found in the plasma of glioblastoma multiforme (GBM) patients help distinguish those with sarcoidosis and healthy patients." (PMID 36619227, 2023).
liver cancer (1 paper, 2022). An epithelial or non-epithelial malignant neoplasm that arises from the liver. "There is currently no reports on the role of PSMG3 AS1 in NAFLD, although NAFLD progression can lead to liver cancer, and PSMG3 AS1 plays a role in liver cancer." (PMID 35846147, 2022).
cancer (4 papers, 2017 to 2023). A tumor composed of atypical neoplastic, often pleomorphic cells that invade other tissues. "This analysis showed that most PSM genes, especially PSME3 and PSMG3, were differentially expressed (frequently overexpressed) relative to normal tissue, further highlighting the importance of the proteasome in cancer development and progression." (PMID 36123629, 2022). "In comparison with the other PSM genes, differential expression of PSMB11 was relatively uncommon, whereas PSME3 and PSMG3 were found to be differentially expressed in virtually all examined cancer forms (15/16 cancer types)." (PMID 36123629, 2022). "As PSME3 and PSMG3 are involved in proteasome activation and assembly, evaluation of their expression levels in cancer could be clinically relevant." (PMID 36123629, 2022). "The expression of PSMG3 has been reported to be upregulated in a variety of cancer tissues." (PMID 29968759, 2018). "It was suggested that PSMG family member overexpression may promote tumor growth, and overexpression of PSMG1, PSMG3, and PSMG4 may further promote the development of cancer metastasis." (PMID 36619227, 2023). "In conclusion, the comprehensive pan-cancer analysis presented here demonstrated that several PSM genes (e.g. PSMA1, PSMB4-5, PSMB8-10, PSMD2, PSMD4, PSMD11, PSME1-3, and PSMG3) may be putative biomarkers for determining prognosis and choice of treatment for different cancer types." (PMID 36123629, 2022).
tumor (3 papers, 2018 to 2026). "Immune deconvolution analyses further demonstrated significant correlations between PSMG3 expression and distinct immune cell populations within the tumor microenvironment." (PMID 41869439, 2026). "Our results indicated that the expression of PSMG3 was also upregulated in the OA synovial tissues, highlighting the tumour-like properties of the OA synovial tissue." (PMID 29968759, 2018).
PSMG3 also shares sentences with these, for which no sentence is quoted: autistic disorder (1 paper); growth disorders (1); liver diseases (1); lung carcinoma (1); sarcoidosis (1); schizophrenia (1).